MMP9 (matrix metallopeptidase 9)
Diseases named in the same sentence as MMP9 in open-access papers (continued):
Sharing a sentence is not in itself a finding about the gene and the disease.
Stroke (continued). "High plasma MMP-9 concentrations in the acute phase of a cerebral infarct are considered as independent predictors of hemorrhagic transformation in all stroke subtypes." (PMID 22587708, 2012). "SDMA levels at 6 hours and MMP-9 levels at 3 days were lower in stroke patients than in controls (P <0.05)." (PMID 23158556, 2012). "Changes corresponding to these altered MMP-9 levels were visualized in vivo using NIR fluorescence imaging of the activated MMPSense750 in the stroke region compared to sham controls." (PMID 22742423, 2012). "Together with platelet-derived growth factor CC, MMP-9 has been involved in BBB breakdown after stroke." (PMID 22082476, 2011). "Stroke up-regulated MMP-9 level in the brain, and acute minocycline treatment reduced its expression in both genders (P < 0.0001)." (PMID 22177314, 2011). "Higher expression levels of COX-2, PGES, MMP-2, and MMP-9 were detected in specimens obtained from the carotid lesions of patients with recent TIA or stroke compared with specimens obtained from asymptomatic patients." (PMID 21457581, 2011). "In this study we evaluated the pharmacogenetic effects of MMP9 and MMP12 variants on CHD, stroke, HF, combined CHD and CVD, and ACM." (PMID 21887284, 2011). "In particular, MMP9 has been known to contribute to hemorrhages after stroke and thrombolysis by t-PA treatment." (PMID 21541054, 2011). "In patients with severe stroke both MMP-2 and MMP-9 have a strong association with edema formation and midline shift." (PMID 21110846, 2010). "In human stroke patients treated with tPA, a similar rise blood MMP-9 occurs by 8 hours and with a return to baseline by 25 hours." (PMID 20406488, 2010). "MMP-9 is upregulated in peri-infarct cortex at 7–14 days after stroke and is colocalized with markers of neurovascular remodeling." (PMID 20514206, 2009). "And during the last decade, an abnormal expression of MMP-9 has been shown to play a deleterious role in brain injury in both animal models of cerebral ischemia and human stroke." (PMID 20514206, 2009). "After experimental stroke, MMP-9 null mice showed reduced blood brain barrier degradation and white matter injury." (PMID 18694515, 2008). "Because MMP-2 and MMP-9 have distinct mechanisms of activation and different roles after stroke, the potential selectivity of minocycline for either enzyme should be determined." (PMID 16846501, 2006). "Minocycline inhibits enzymatic activity of gelatin proteases activated by ischemia after experimental stroke and is likely to be selective for MMP-9 at low doses." (PMID 16846501, 2006). "MMP-9 increases following experimentally induced stroke, and the availability of this proteinase directly contributes to the size of the infarct." (PMID 16156894, 2005). "This study evaluated whether serum levels of mature BDNF, proBDNF, and matrix metalloproteinase-9 (MMP-9) can predict functional recovery after stroke." (PMID 41758865, 2026). "A study has shown that higher levels of MMP-9 in the serum at the onset of stroke could serve as a predictor of unfavorable stroke outcomes." (PMID 40364646, 2026). "The combination of endothelial cell response processes to stroke implies that pericytes may use MMP‐9 to actively migrate from endothelial cells to affected areas and participate in vascular remodeling and repair of NVU after stroke." (PMID 41395456, 2025). "Additionally, MMP-3 and MMP-12 expression is significantly upregulated post-stroke: MMP-3 activates pro-MMP-9, amplifying the proteolytic cascade; MMP-12 further exacerbates neurovascular injury by promoting inflammatory cell infiltration." (PMID 41480312, 2025). "These seemingly conflicting observations can be explained by the temporal dynamics and cell-type specificity of miR-21 activity: during the acute phase of stroke, early upregulation of miR-21 in neurons or reactive astrocytes contributes to MMP-9–mediated injury." (PMID 40981170, 2025).
Stroke (continued). "Likewise, while our analysis identified SPOCK1 and BCAN as ECM-related markers, other studies found ECM proteins like fibulin-1, fibronectin, and MMP9 elevated in stroke, highlighting consistent engagement of tissue remodeling pathways across stroke types." (PMID 41152969, 2025). "Regarding MMP-9, previous studies have shown that it is associated with infarct volume but not with stroke severity, consistent with our findings." (PMID 40821836, 2025). "Notably, MMP-9 levels significantly increase following stroke, contributing to extracellular matrix degradation and leukocyte infiltration, thereby amplifying the inflammatory response." (PMID 40066310, 2025). "However, rosuvastatin treatment prevented progressive kidney inflammation and fibrosis in stroke-prone rats by preventing the decrease in MMP-9 activity." (PMID 40862456, 2025). "Yet, the role of PD-L1 after stroke remains unclear as another group showed that PD-L1 mediates Treg suppression of neutrophil-derived matrix metalloproteinase-9 (MMP-9), an enzyme contributing to BBB breakdown." (PMID 39368872, 2025). "Similarly, combining atorvastatin with tPA reduced MMP-9 levels, lowered the incidence of hemorrhagic transformation, and extended the therapeutic window to 6 h in a rat stroke model." (PMID 39273389, 2024). "Subsequently, this heightened MMP9 level post-stroke may have implications for outcomes such as infarct volume and brain edema." (PMID 39309404, 2024). "Understanding the impact of MMP-9 on post-stroke neuronal excitability could have therapeutic implications, potentially targeting MMP-9 to modulate epileptic outcomes after stroke." (PMID 38255970, 2024). "Studies of human brains report upregulation of both MMP-3 and MMP-9 following stroke." (PMID 39000490, 2024). "report an increase in both ox‐LDL and MMP‐9 in patients with unstable plaques after stroke." (PMID 39039803, 2024). "Since MMP-9 has been implicated in plasticity and recovery during the later phases of stroke, it is plausible that the interaction between MMP-9 and aspirin in asymptomatic SBI may have distinct characteristics." (PMID 39850789, 2024). "And, while it remains unclear if MMP-9 specifically cleaves basement membrane laminin during stroke pathogenesis, the involvement of neutrophil-derived proteinases in pathologies affecting the CNS are likely inextricably linked to basement membrane biology." (PMID 39707430, 2024). "Furthermore, MMP-9, which involves neuroplasticity, has a peak in the early subacute phase post-stroke." (PMID 39599732, 2024). "Additionally, elevated MMP-9 concentrations during the acute phase are independent predictors of HT across all stroke subtypes." (PMID 39606238, 2024). "This increased MMP9 response might be particularly significant following a stroke in elderly individuals." (PMID 39309404, 2024). "Considering the pleiotropic effects of MMP-9, including its pro-inflammatory impact and blood–brain barrier damage, especially in the acute phase of stroke, this result may reflect lingering effects." (PMID 38891934, 2024). "MMP9 is a component of the extracellular matrix that increases after stroke." (PMID 39507105, 2024). "Hence, studies on MMP-9 and other inflammatory markers should be wary of changes in interpretation depending on the time of collection after the stroke." (PMID 41542283, 2024). "The authors concluded that the cut-off value of 390.7 for MMP-9 could predict the development of post-stroke cognitive impairment with 56.41% sensitivity and 81.37% specificity." (PMID 41542283, 2024). "Thus, it is pertinent to investigate the potential role of MMP-9 in facilitating post-stroke recovery during this critical phase." (PMID 38891934, 2024). "Studies suggested that level of MMP-2 and MMP-9 significantly increases in the brain after stroke." (PMID 39654616, 2024).
Stroke (continued). "This study provides insights into the relationship between MMP-9 levels and post-stroke epileptogenesis, suggesting that MMP-9 may play a role in modulating seizure susceptibility after ischemic stroke." (PMID 38255970, 2024). "In contrast to other common anticoagulants such as citrate and low-molecular-weight heparin (LMWH), high-molecular-weight heparin (HMWH) induces the expression of matrix metalloproteinase (MMP)-9, which is also measured as a biomarker for stroke in blood samples." (PMID 39337591, 2024). "Degree of change in MMP-9 levels from baseline to a month after stroke was neither positively nor negatively associated with patient outcome." (PMID 41542283, 2024). "Female MMP-3 KO stroke brains also had decreased expression of blood cell adhesion genes Pecam1 and Icam2, and decreased expression of inflammatory response genes Ccr1, Cxcl1, Mmp9, Il4ra, Il6, and Il1rn." (PMID 39000490, 2024). "Consistent with other findings that infiltrated neutrophils expressed MMP-9 post stroke, our double-immunostaining also showed that MMP-9 was found in infiltrated neutrophil and monocytes outside the vascular compartment, whereas MMP-2 was only detected in the vascular compartment." (PMID 39273389, 2024). "The dynamics of MMP-2 and MMP-9 activity reflect their multifunctional roles in stroke." (PMID 37511788, 2023). "Hence, the aim of the present study was to evaluate the prognostic value of proteins VEGF, IGF-1 and MMP-9 and the expression of their genes as markers of recovery in stroke patients." (PMID 37371326, 2023). "We also found that Ripk2 knockout mice had greater preservation of tight junction proteins Zona occludens-1 (ZO-1) and Occludin in the ipsilateral cortex 24 h after stroke, which was concurrent with lower levels of active-MMP-9, a major contributor to BBB opening." (PMID 37777791, 2023). "Furthermore, those pathological processes probably explain recent results indicating that MMP-9 levels measured in the acute phase of stroke have predictive value for post-stroke cognitive impairment (PSCI) three months after stroke." (PMID 37371326, 2023). "Subsequently, the damaged BBB could promote more neutrophils infiltration, which in turn produced more MMP9 and ROS, eventually amplifying oxidative stress and neuroinflammation after stroke." (PMID 37180174, 2023). "Therefore, the present study examines the expression of VEGF, IGF-1 and MMP-9 proteins and their genes to identify biomarkers that can prognose brain repair ability and thus estimate the outcome of stroke." (PMID 37371326, 2023). "Our findings indicate that combined MMP9 protein and mRNA expression might be a useful biomarker for cognitive improvement in post-stroke patients, demonstrating 87% sensitivity and 71% specificity (p < 0.0001)." (PMID 37371326, 2023). "Furthermore, in cases of acute stroke, the serum MMP-9 level was found to predict post-stroke cognitive impairment three months later." (PMID 37371326, 2023). "MMP-9 is upregulated in the peri-infarct region 7–14 days after stroke and may be involved in vascular remodeling." (PMID 37840921, 2023). "MMP-9 is also involved in the immune response during strokes." (PMID 37206663, 2023). "Thus, inhibition of MMP-9 on the first day after stroke has a positive effect on its outcome; on the third day, there is no neuroprotective effect; and on the seventh day, it leads to an increase in damage." (PMID 37511788, 2023). "Our data suggest that astrocytes may secrete BDNF and MMP9, which promote neuron survival, synaptic plasticity and angiogenic remodeling during stroke recovery." (PMID 37744881, 2023). "MMP-9 was also assessed because its expression is related to BBB disruption, and we noted that even by 6 h following stroke there appeared to be a trend for more MMP-9-positive cells in the ipsilateral hemisphere of tPA + vehicle-treated mice than in mice treated with vehicle only." (PMID 37397458, 2023).
Stroke (continued). "MMP-9 levels correlate with infarct volume, stroke severity, and functional outcomes." (PMID 36691064, 2023). "The study found that MMP-9 is closely related to the structure of the blood vessel wall and the permeability of the blood-brain barrier, which can reflect the edema area and the degree of cerebral infarction in stroke patients." (PMID 36865742, 2023). "MMP-9 showed a good predictive capacity for haemorrhagic transformation but low sensitivity in the differentiation between ischemic and haemorrhagic stroke and in stroke diagnosis." (PMID 37511304, 2023). "Matrix metalloproteinase-9 (MMP-9) is detrimental in the acute phase but could be beneficial for recovery in the subacute phase of stroke by breaking down CSPGs." (PMID 35743941, 2022). "MMP-2 and MMP-9 are considered molecular biomarkers of neuroinflammation in stroke studies." (PMID 35743229, 2022). "MMP-9 is a zinc- and calcium-dependent proteolytic enzyme that can participate in the degradation of the BBB in rtPA-associated hemorrhagic complications after stroke." (PMID 35359227, 2022). "The TLR4/MMP9-mediated reduction of astrocyte reactivity after ECS activation via CB2R is of special interest for stroke, as it has been suggested elsewhere that attenuation of the inflammatory process could be neuroprotective after tMCAO in rats." (PMID 35721207, 2022). "Moreover, in the stroke plus AD unified models, there was an increase in MMP-9 expression and astrogliosis due to the effect of ischemic neuroinflammation at 24 h." (PMID 35743229, 2022). "Experiments in animals have shown that MMP-9 was upregulated in areas of cerebral ischemia and that a breakdown of the blood-brain barrier led to brain swelling, hemorrhage, and neurotoxic cell death in the early stages of stroke." (PMID 36092813, 2022). "Consistent with our results, a persistent increase in MMP-9 has been reported in stroke." (PMID 36092813, 2022). "The disorder of MMP9 gene level may participate in the pathophysiological process of stroke, and may become a new molecular target for diagnosis and prognosis of stroke patients." (PMID 34313877, 2022). "Upregulation of MMP-9 has been well known to cause BBB breakdown and recruitment of inflammatory cells related to the pathologic processes of many brain insults, such as Alzheimer’s disease, stroke, and tumor metastasis." (PMID 35054789, 2022). "Significant increases in MMP-9 activity were also found in individuals who had a previous stroke." (PMID 35627746, 2022). "Moreover, T regulatory cells provide neurovascular protection against stroke by inhibiting peripheral neutrophil-derived MMP-9 production, but these studies were only performed in young animals." (PMID 34711943, 2022). "Furthermore, edaravone has been shown effective in recovery in stroke patients and reduce the MMP-9 levels." (PMID 35204290, 2022). "MMP-9 was reported to relate with functional outcome and spontaneous HT after stroke." (PMID 36009063, 2022). "Taken together with the processes involved in endothelial cells’ response to stroke, pericyte activation and secretion of MMP-9 represents an intermediate step between leakage by transcytosis (a form of transcellular leakage) and eventual TJ degradation (paracellular leakage)." (PMID 36139398, 2022). "This implies that pericytes may use MMP-9 to actively migrate from the endothelium to the impacted area to participate in post-stroke revascularization and repair of the NVU." (PMID 36139398, 2022). "For that, we used two relevant stroke biomarkers, c-Fn, and MMP9." (PMID 36296077, 2022). "For instance, increased levels of MMP-9 are found after stroke." (PMID 36311773, 2022). "Additionally, these increased MMP-9 levels correlate with the degree of cerebral edema in rodent models of stroke." (PMID 36446955, 2022). "Moreover, compared to the Sham ChP, a significant increase in the expression of MMP9 protein was detected in the Veh-treated stroke ChP (p < 0.001)." (PMID 35413993, 2022).
Stroke (continued). "Furthermore, MMP-9 expression was clearly correlated with the presence of granulocytes in models of stroke and ischemia-reperfusion injury, in which neutrophils were considered the main source of MMP-9." (PMID 36034148, 2022). "Although MMP-9 may be involved in the pathophysiologic process of stroke and depression, whether it plays an important role in depression after stroke is uncertain." (PMID 35370878, 2022). "This study investigated the efficacy of delayed post-conditioning neuroprotection in modulating the infarct volume, brain edema, BBB disintegration, neurological deficits, and MMP-9 levels after delayed thrombolysis in an embolic model of stroke in female rats." (PMID 35432799, 2021). "MMP-2 and MMP-9 are the most studied and main MMPs that are increased following stroke." (PMID 34483842, 2021). "Whereas the role of NF-κB and the proteasome under stroke conditions has already been shown, the mutual interaction between MMP-9 and ABCB1 on the one hand and NF-κB on the other hand has just recently been described by us in a murine stroke model." (PMID 34483846, 2021). "Interestingly, monocytes/macrophages express molecules that enhance angiogenesis such as VEGF, TGF-β and MMP-9 providing post-stroke recovery." (PMID 34572077, 2021). "Butylphtalide increases the VEGF and MMP-9 in animal models of stroke and might be used as key biomarkers in the management of stroke, but data in humans are lacking." (PMID 34987460, 2021). "This study showed that butylphthalide could decrease the MMP-9 levels after stroke more effectively than conventional treatments alone." (PMID 34987460, 2021). "Conversely, in plasma samples collected at 12, 24, and 48 h after symptoms onset in 39 patients with ischemic stroke, while MMP-9 concentrations were greater in stroke patients than the reference interval for healthy controls, no significant changes were reported over time." (PMID 33633673, 2021). "Therefore, to evaluate the effects of VT treatment on inflammatory responses after stroke, we measured the expression of MMP9 in IBZ and M1 macrophage number using ED1 immunostaining." (PMID 33346402, 2021). "Already, the involvement of MMP-2 and MMP-9 has been extensively studied in stroke." (PMID 34299322, 2021). "Indeed, stroke enhanced both protein abundance and activity of MMP-9 at 24 h poststroke when compared to sham mice, which was even further enhanced when mice were treated with cerulenin." (PMID 34483846, 2021). "Background and Purpose: Butylphtalide increases the vascular endothelial growth factor (VEGF) and decreases matrix metalloproteinase (MMP)-9 in animal models of stroke and might be of use in the management of stroke." (PMID 34987460, 2021). "In the early post-stroke phase, Tregs act on peripheral leucocytes to inhibit the production of matrix metalloproteinase-9 (MMP-9) by neutrophils, thereby protecting the blood–brain barrier, and prevent the activation of effector T cells by secreting anti-inflammatory IL-10 and TGF-β." (PMID 35008440, 2021). "No sex differences were reported for plasma levels of tissue inhibitor metalloproteinase 1 (TIMP-1) and insulin-like growth factor 1 (IGF-1) 1 day after stroke, matrix metalloproteinase 2 (MMP2) within 2 days after stroke, and matrix metalloproteinase 9 (MMP9) 2 days and 1 month after stroke." (PMID 34858141, 2021). "Hence, decreasing the MMP-9 levels promptly after stroke onset is conducive to limiting the extent of brain injury." (PMID 34987460, 2021). "Using a murine stroke model, our group was able to show that stimulation of the proinflammatory NF-κB pathway results in both enhanced MMP-9 activity and increased ABCB1 transporter activity, all of which leading to BBB breakdown, cell death and impaired neurological recovery." (PMID 34483846, 2021).